DHX38 (DEAH-box helicase 38)
Description:
Probable ATP-binding RNA helicase (Probable). Involved in pre-mRNA splicing as component of the spliceosome.
Synonyms: DDX38; KIAA0224; PRP16; hPrp16; PRPF16; RP84
Tractability: Small molecule: a structure with a bound ligand is known. PROTAC: UniProt records ubiquitination sites on it; ubiquitination databases record sites on it; its protein half-life has been measured.
Gene: Protein-coding gene on chromosome 16 (72,093,613 to 72,112,912, forward strand). Ensembl gene ENSG00000140829.
Subcellular location: Nucleus
Subcellular location (Human Protein Atlas): Nucleoplasm
Pathways (Reactome):
Metabolism of RNA: Transport of Mature mRNA derived from an Intron-Containing Transcript; mRNA 3'-end processing; mRNA Splicing - Major Pathway
Disease: Dengue Virus-Host Interactions
Gene Ontology:
Molecular function: protein binding; RNA binding; 3'-5' RNA helicase activity; RNA helicase activity; ATP binding; ATP hydrolysis activity; ATP-dependent activity, acting on RNA; nucleic acid binding
Biological process: mRNA splicing, via spliceosome
Cellular component: catalytic step 2 spliceosome; membrane; nucleoplasm; nucleus; spliceosomal complex; U2-type catalytic step 1 spliceosome; ribonucleoprotein complex
Genetic constraint (gnomAD): Loss-of-function variants: 100 observed, 156.99 expected, observed/expected ratio (o/e) 0.64, 90% interval 0.54 to 0.75. The upper end of that interval is the gene's LOEUF score, 0.75, which puts it in group 3 of 6, group 1 being the genes least tolerant of losing a copy. Missense variants: 1,437 observed, 1,699.7 expected, observed/expected ratio (o/e) 0.85, 90% interval 0.81 to 0.88. Synonymous variants: 649 observed, 647.9 expected, observed/expected ratio (o/e) 1, 90% interval 0.94 to 1.07.
Homologues: Orthologues: chimpanzee DHX38 (99% identical), macaque DHX38 (99% identical), guinea pig DHX38 (98% identical), dog DHX38 (98% identical), pig DHX38 (98% identical), rabbit DHX38 (98% identical), rat Dhx38 (98% identical), mouse Dhx38 (97% identical), tropical clawed frog dhx38 (83% identical), zebrafish dhx38 (82% identical), Drosophila melanogaster Prp16 (62% identical), Caenorhabditis elegans mog-1 (55% identical). Paralogues in human: DHX8 (37% identical), DHX16 (32% identical), DHX15 (26% identical), DHX35 (24% identical), DHX33 (23% identical), DHX37 (21% identical), DHX40 (20% identical), DHX34 (20% identical), DHX57 (20% identical), DHX29 (19% identical), YTHDC2 (19% identical), DHX9 (18% identical), and 6 more.
Diseases named in the same sentence as DHX38 in open-access papers:
DHX38 is named in the same sentence as 26 diseases in open-access papers, as found by Europe PMC text mining. Sharing a sentence is not in itself a finding about the gene and the disease. The quoted sentences say what the papers report.
retinitis pigmentosa (8 papers, 2017 to 2025). Retinitis pigmentosa (RP) is an inherited retinal dystrophy leading to progressive loss of the photoreceptors and retinal pigment epithelium and resulting in blindness usually after several decades. "Previous studies have suggested that dhx38 is associated with non-syndromic retinitis pigmentosa (RP)." (PMID 39857604, 2024). "A previous study identified a missense mutation in dhx38 that caused early-onset retinitis pigmentosa with macular coloboma." (PMID 39857604, 2024). "The DHX38 gene is associated with early onset retinitis pigmentosa (eoRP), and MC was discovered in DHX38-eoRP." (PMID 36429029, 2022). "Interestingly, the autosomal recessive mutation G332D in DHX38, the human ortholog of Prp16, is associated with retinitis pigmentosa; however, its requirement for introns with diverse sizes and splicing signatures remains understudied." (PMID 40065603, 2025). "DHX38 is a slicing factor that is involved in the etiology of early-onset retinitis pigmentosa." (PMID 35101047, 2022).
ovarian clear cell cancer (2 papers, 2022 to 2024). An invasive malignant neoplasm that arises from the ovary and is characterized by a predominance of clear and hobnail malignant epithelial cells. "By employing a CRISPR‐Cas9 screen, we uncovered DHX38/PRP16 as a novel genetic vulnerability whose knockdown results in growth suppression of ovarian clear cell carcinoma both in vitro and in vivo." (PMID 34965029, 2022). "DHX38/PRP16 may have a role in the carcinogenesis of ovarian clear cell carcinoma (OCCC), indicating its potential as a therapeutic target." (PMID 39857604, 2024).
pancreatic ductal adenocarcinoma (2 papers, 2023 to 2024). An infiltrating adenocarcinoma that arises from the epithelial cells of the pancreas. "Here, we described the role of alternative splicing gene RELL2 and its upstream splicer DHX38 in pancreatic ductal adenocarcinoma." (PMID 37506056, 2023).
retinal disease (2 papers, 2017 to 2021). "A subset of patients was screened for mutations in retinal disease genes, and mutations in the following genes were found: three cases with USH2A; three cases with EYS; one case each with USH3A (CLRN1), DHX38, RHO, RPGR, and RP9." (PMID 33037922, 2021).
acute myeloid leukemia (1 paper, 2022). Acute myeloid leukemia (AML) is a group of neoplasms arising from precursor cells committed to the myeloid cell-line differentiation. "Consistent with our result, amplification of DHX38/PRP16 has been found in as many as 56% of acute myeloid leukemia specimens as well as in established acute myeloid leukemia cell lines." (PMID 34965029, 2022).
atherosclerosis (1 paper, 2023). A disease characterized by the build-up of fatty material and calcium deposition in the arterial wall resulting in partial or complete occlusion of the arterial lumen. "We used the endothelial marker gene CDH5 to identify a cluster of endothelial cells and confirmed that these cells express DHX38, MAT2A, CCDC92, FES and FURIN, prompting future efforts to dissect the role of these genes in this cell type in atherosclerosis." (PMID 36928188, 2023).
Blindness (1 paper, 2020). Blindness is the condition of lacking visual perception defined as a profound reduction in visual perception. "In two siblings with intellectual disability, psychomotor retardation, blindness, epilepsy, movement disorder and cerebellar atrophy we identified rare homozygous variants in the genes LTBP1, EMILIN1, CACNB4, MINAR1, DHX38 and MYO15 by whole-exome sequencing." (PMID 32176688, 2020).
colorectal carcinoma (1 paper, 2022). A malignant epithelial neoplasm that arises from the colon or rectum and invades through the muscularis mucosa into the submucosa. "Recently, DHX38/PRP16 has been implicated in the proliferative potential of the HCT116 colorectal carcinoma cell line, where cells harboring an active KRAS mutant become responsive to DHX38/PRP16 knockdown." (PMID 34965029, 2022).
endothelial dysfunction (1 paper, 2023). In vascular diseases, endothelial dysfunction is a systemic pathological state of the endothelium (the inner lining of blood vessels) and can be broadly defined as an imbalance between vasodilating and vasoconstricting substances produced by (or acting on) the endothelium. "While our results suggest that DHX38 influences CAD risk by modulating endothelial dysfunction and senescence, it is possible that part of the CAD association signal at the locus is also due to nearby variants in weak linkage disequilibrium that associate with LDL-C." (PMID 36928188, 2023).
epithelial ovarian cancer (1 paper, 2022). "The only gene found to be significantly enriched in ovarian cancer cell lines was the splicing factor DHX38/PRP16." (PMID 34965029, 2022). "We found that out of 14 clinically relevant lineages tested, only epithelial ovarian cancer was significantly (P < 0.001) likely to display a more negative DHX38/PRP16 dependency score compared to all other cell lines." (PMID 34965029, 2022).
inner ear diseases (1 paper, 2024). "However, since hearing abnormalities are common in syndromic forms of RP, our results suggest that the RP in some DHX38-mutation patients may represent a syndromic form, which may also have inner ear disorders." (PMID 39857604, 2024).
infection (1 paper, 2023). The state of being infected such as from the introduction of a foreign agent such as serum, vaccine, antigenic substance or organism. "In RNA-seq experiments with a sgRNA targeting DHX38 (seven days post-infection, TNFα treatment), DHX38 was not down-regulated and we found few reads mapping to DHX38 with Cas9-mediated indels (<2%)." (PMID 36928188, 2023).
tumor (1 paper, 2022). "Additionally, several families of splicing factors, including the DDX/DHX family of RNA helicases to which DHX38/PRP16 belongs, have long been implicated in tumor progression and cellular proliferation." (PMID 34965029, 2022). "The present study highlights the importance of DHX38/PRP16 for the tumorigenicity of OCCC; its knockdown induces apoptosis in vitro and prevents tumor formation in vivo." (PMID 34965029, 2022).
DHX38 also shares sentences with these, for which no sentence is quoted: cancer (2 papers); autosomal-recessive, nonsyndromic deafness (1); Cerebellar atrophy (1); epilepsy (1); Intellectual disability (1); Leber congenital amaurosis (1); leukemia (1); macular coloboma (1); movement disorder (1); nematode infection (1); Onset (1); ovarian cancer (1); pancreatic cancer (1).